RNU6-1175P (RNA, U6 small nuclear 1175, pseudogene)
Gene: Small nuclear RNA gene on chromosome 11 (70,075,363 to 70,075,469, forward strand). Ensembl gene ENSG00000202070.
Homologues: Orthologues: chimpanzee U6 (98% identical), guinea pig U6 (91% identical), dog U6 (89% identical), rabbit U6 (88% identical). Paralogues in human: RNU6-116P (94% identical), RNU6-11P (94% identical), RNU6-37P (94% identical), RNU6-1 (93% identical), RNU6-15P (93% identical), RNU6-19P (93% identical), RNU6-2 (93% identical), RNU6-23P (93% identical), RNU6-3P (93% identical), RNU6-4P (93% identical), RNU6-5P (93% identical), RNU6-6P (93% identical), and 1288 more.